TNF (tumor necrosis factor)
Diseases named in the same sentence as TNF in open-access papers (continued):
Sharing a sentence is not in itself a finding about the gene and the disease.
colorectal cancer (continued). "Colorectal cancer cells in culture made little LAMA5, but its levels were increased by culture in a medium conditioned by tumour-derived CD11b+ myeloid cells through TNFα/NFκB pathway signalling." (PMID 31064120, 2019). "In recurrent colorectal cancers, the levels of positive regulators of SERPINB2, such as TNF (Z-score = 5.021, p-value = 0.301), JUNB (Z-score = 1.533, p-value = 0.00515) and ERK (Z-score = 3.763, p-value = 0.171), were also increased." (PMID 30965654, 2019). "Unconditional logistic regression analysis of colorectal cancer risks according to tertiles of zinc-α2-glycoprotein (ZAG), leptin, high-molecular-weight adiponectin (HMW-ADPN), and tumor necrosis factor-alpha (TNF-α) in all subjects." (PMID 29755407, 2018). "Angiogenesis in various tumors such as colorectal cancer is mediated by different molecules such as IL-1β, bFGF, VEGF, MMPs, and TNFα." (PMID 30127820, 2018). "All colorectal cancer cell lines tested produced CXCL11 after stimulation with the cytokines IFNγ and TNFα, as evidenced by qRT-PCR and by ELISA." (PMID 29163806, 2017). "In other colorectal cancer cells, SW48 cells, EM treatment slightly decreased TNFα-stimulated or IL-1β-stimulated NF-κB promoter transcriptional activities in a dose-dependent manner." (PMID 28584401, 2017). "Clinical studies have revealed that expression of TNF-α and IL-6 and activation of NF-κB and STAT3 are increased in patients with active UC and particularly in those who progress to colorectal cancer." (PMID 28300788, 2017). "Administration of DSR-29133 leads to the induction of IFNα/γ, IP-10, TNFα, IL-1Ra and IL-12p70, and to a reduction in tumor burden in syngeneic models of renal cancer (Renca), metastatic osteosarcoma (LM8) and colorectal cancer (CT26)." (PMID 26959743, 2016). "In a study on colorectal cancer, cannabinoid receptor (CB1 and CB2) agonists were shown to have an effect on apoptosis through a TNFα-mediated increase in ceramide production." (PMID 26379708, 2015). "TNFα, a key regulator of the inflammatory response, can also increase the expression of transcription factor Snail and induce EMT in colorectal cancer cells." (PMID 24489910, 2014). "In this study, we show for the first time that TNFα significantly reduced CYP27B1 mRNA expression and expression of the calcium ion channel TRPV6 in colorectal cancer cells." (PMID 24120915, 2014). "In this study, we showed that TNFα induces EMT in human HCT116 cells and thereby promotes colorectal cancer (CRC) invasion and metastasis." (PMID 23431386, 2013). "TNFα and IL-17 cooperatively stimulated glycolysis in HT-29, T84, Caco-2 and HCT116 colorectal cancer cells." (PMID 23866118, 2013). "By activating PI3K/AKT and ERK growth pathways and inhibiting the BAD and TNFα-mediated apoptosis, the IGF-1R signaling pathway promotes the survival, growth, and metastasis of colorectal carcinomas." (PMID 24182354, 2013). "Frequency of the combined genotypes (TNFα-1031T/C & NOD2 3020insC) and changes in the OR with increasing age of diagnosis in consecutively collected colorectal cancer patients." (PMID 18433468, 2008). "TNF-α and IL-6, which are pleiotropic cytokines, may have anti-tumour properties, and may be of benefit as chemotherapy agents in experimental cancer and even in the clinical treatment of colorectal cancer, and might act in synergy with conventional chemotherapeutics such as 5-FU." (PMID 12237767, 2002). "Data analysis indicated that quercetin may mitigate the inflammatory impact in colorectal cancer (CRC) treatment by inhibiting the formation and expression of TNF-α." (PMID 40978482, 2025). "WBE, capable of inhibiting the secretion of IL-1β, IL-6, and TNF-α in LPS-stimulated RAW 264.7 macrophages, may contribute to the attenuation of inflammation in colorectal cancer." (PMID 41463421, 2025).
colorectal cancer (continued). "This study evaluated esketamine's effects on serum biomarkers of oxidative stress (glutathione, catalase, malondialdehyde, superoxide dismutase), inflammatory mediators (TNF-a, CRP IL-6), and T lymphocyte subsets in patients undergoing laparoscopic colorectal cancer resection." (PMID 40951888, 2025). "We discovered that BZA treatment increases the expression of TNF-α and the IAP family of proteins suggesting that BZA treatment in combination with SMAC-mimetics could co-operatively induce apoptosis in colorectal cancer." (PMID 38600086, 2024). "Significant differences were observed between patients with gastric and colorectal cancer experiencing CAC, showing that increased IL-6 was found in patients with gastric cancer CAC and patients with colorectal cancer CAC exhibiting high IL-6, TNF-α, platelet, white blood cell count, FFA, and ApoA." (PMID 38730660, 2024). "In breast cancer, andrographolide has been shown to inhibit COX-2 expression by reducing p300 HAT activity and impede angiogenesis via the VEGF pathway; in human colorectal cancer HCT116 cells, andrographolide acts as an antagonist of TNF-α-induced IL-8 production." (PMID 38148335, 2024). "This study successfully constructed EpCAM-CAR cells and found that they can target and recognise EpCAM-positive tumour cells, secrete killer cytokines TNF-α and IFN-γ and better inhibit the growth and metastasis of colorectal cancer in vitro and in vivo than unmodified T cells." (PMID 39107717, 2024). "On the other hand, colorectal cancer patients who responded efficiently to chemotherapy presented a negative NES in KEGG pathways such as IL-17 signaling pathway, TNF signaling pathway, Chemokine signaling pathway, Cellular senescence, and Cytokine-cytokine receptor interaction." (PMID 39336151, 2024). "CRP, procalcitonin, TNF‐α, IL‐6, IL‐10, and WBC have been used as the most common markers of inflammatory stress, and Chen used these indices to compare the efficacy of laparoscopic surgery and conventional surgery in the treatment of colorectal cancer." (PMID 38351544, 2024). "The increased sensitivity found in the LLC and colorectal cancer lines confirms that the function of Mgat5 in limiting the response of cells to TNF-α is not restricted to PDAC." (PMID 38912584, 2024). "TNFRSF12A, alternatively named FN14, belongs to the TNF/TNFR superfamily and has been reported to be involved in the initiation and progression of multiple tumor types, including glioma, pancreatic, breast, non-small-cell lung cancer, and colorectal cancer." (PMID 38660262, 2024). "Furthermore, as part of the interactions among inflammatory cytokines, TNF, as such a mediator, can induce IL-6 expression in colorectal carcinomas, inducing therapeutic benefits in CRC clinical trials through IL-6 inhibition and anti-TNF therapies." (PMID 38338927, 2024). "In addition, TNF-α was reported to induce EMT and promote the metastasis and invasion of colorectal cancer." (PMID 38068712, 2023). "Interestingly, both TNFα and NFκB expression are upregulating MACC1 expression in colorectal cancer cells." (PMID 37627117, 2023). "Moreover, colorectal cancer-infiltrated eosinophils have been shown to promote IFN-γ and TNF-α production by CD8+ T cells via the GM-CSF-IRF5 signalling axis, thereby augmenting antitumour immune responses." (PMID 38106991, 2023). "Here, we aimed to evaluate, for the first time, the effect of anti-TNFα mAb on the tumor microenvironment in the absence of intestinal inflammation in a colorectal cancer orthotopic transplant mouse model suitable for tumor microenvironment assessment." (PMID 36996146, 2023). "Recent studies have reported that miR-539 can activate the stress-activated protein kinase/jun N-terminal kinases (SAPK/JNK) signaling pathway by targeting tumor necrosis factor (TNF) -α-induced protein 8 (TIPE) and reduce the expression of GPX4 to inhibit ferroptosis in colorectal cancer cells." (PMID 37369681, 2023).
colorectal cancer (continued). "The active form of TNF-α was detected in the colon tissues in patients with UC and colorectal cancer but not in healthy individuals." (PMID 35865942, 2022). "Similarly, lipopolysaccharide (LPS) is a substance that induces the inflammation process and can be promoted by TNF-α and Interferon-γ (IFN-γ) in colorectal cancers." (PMID 35681644, 2022). "Moreover, the TNF-stimulated phosphorylation of ERK, p38, AKT, and STAT3 was decreased in both colorectal cancer cell lines." (PMID 35222445, 2022). "Without exogenous TNF stimulation, roburic acid also inhibited the expression of these antiapoptotic proteins in colorectal cancer cells." (PMID 35222445, 2022). "Based on the previous results, we found that anti-TNF drugs can reduce the incidence of colorectal cancer not only in IBD patients but also in other disease groups." (PMID 36618924, 2022). "Another study found that the incidence of CRC decreased in the RA group, while in the anti-TNF group, in contrast to other RA groups, no reduction in colorectal cancer was observed." (PMID 36618924, 2022). "Colorectal cancer cells displayed no significant increase of autophagic objects, but the addition of recombinant human TNFα protein in concentration 100 ng/ml increased autophagy in HT29 cells (data not shown)." (PMID 33957885, 2021). "Previous studies reported that inflammatory cytokines like members of the tumor necrosis factor (TNF)-superfamily could change the tumor microenvironment and promote the progression of colorectal cancer through activation of EMT." (PMID 33937049, 2021). "Moreover, andrographolide antagonizes TNF-α-induced IL-8 via inhibition of the NADPH oxidase/ROS/NF-κB and Src/MAPKs/AP-1 axes in human colorectal cancer HCT116 cells and suppresses angiogenesis in the tumor microenvironment." (PMID 33374961, 2020). "In addition, TNF-α and IL-8 have been shown to facilitate NET formation and these cytokines are highly expressed by a number of tumour types, including colorectal cancer." (PMID 28828191, 2017). "Furthermore, in subsequent studies, the largest number of mRNA copies for TNF-α and TNFR2/R7 in healthy cells surrounding cancer tissue in patients with stage III of colorectal cancer (compared to a group of lower degree of stage of the disease) was observed." (PMID 27110571, 2016). "TNF was similarly observed in the colons of patients with active ulcerative colitis and advanced colorectal cancer, but not in normal mucosa." (PMID 24212934, 2011). "More recently, TNFα, Hepatocyte Growth Factor, PDGF and FGF19 and IL-1β have been shown to activate Wnt/β-catenin signaling, the oncogenic pathway activated in the majority of colorectal cancers." (PMID 20661477, 2010). "There is a trend to TNF-α and IFN-γ suppression with IL-10 promotion as colorectal cancer advances." (PMID 16641913, 2006). "LPS-induced production of TNF-α and of IFN-γ was reduced in patients with colorectal carcinoma compared to controls (TNF-α, 11 269 pg ml−1{12 598}; IFN-γ, 0.00 pg ml−1{226}; median {IQR}) (TNF-α, 20 576 pg ml−1{11 637}, P< 0.0001; IFN-γ, 1048 {2428}, P = 0.0051, Mann–Whitney U -test)." (PMID 10737381, 2000). "Looking forward, with the dual roles of TNF - α and the potential of TNFR2 as a therapeutic target, further comprehensive and long-term studies are warranted to clarify their precise mechanisms in CRC, optimize related therapies, and ultimately improve the prognosis for colorectal cancer patients." (PMID 39980561, 2025). "Preoperative hyperthermia could improve the immune responses to surgical stress by decreasing the plasma concentration of TNF-α without enhancing the quality of recovery after colorectal cancer surgery." (PMID 36765695, 2023). "The therapies developed against these studied cytokines—IL-1β, IL-6, and TNF-α—can represent alternatives to current chemotherapeutic and immunological treatments, considering the toxicity and lack of effectiveness of chemotherapy in colorectal cancer." (PMID 38137862, 2023).
colorectal cancer (continued). "Importantly, roburic acid inhibited the TNF-induced phosphorylation of IKKα/β, IκBα, and p65, degradation of IκBα, nuclear translocation of p65, and NF-κB-target gene expression, including that of XIAP, Mcl-1, and Survivin, in colorectal cancer cells." (PMID 35222445, 2022). "In the current study, we found that roburic acid could significantly downregulate Cyclin D1 and c-Myc protein levels in colorectal cancer cells, with or without TNF stimulation." (PMID 35222445, 2022). "In colorectal cancer cell lines, TNF-α and TGF-β induce EMT-like changes in an NLRP3/Snail1 axis-dependent manner, with Snail being stabilized and protected from degradation in response to TNF-α signaling, helping complete EMT and promote cancer cell migration and metastasis." (PMID 34576042, 2021). "In addition to its effects in the gastric body, H. pylori colonization in the mouse intestinal tract has been shown to increase production of c-myc, interleukin-1 (IL-1), IL-6, and tumor necrosis factor (TNF), but reduced interferon-gamma (IFN-γ), with subsequent development of colorectal cancer." (PMID 34360663, 2021). "In T3/T4 colorectal cancer, the number of NKp44+ ILC3s and the expression of LTA, LTB, and TNF, but not ILC3-related molecules (e.g., RORC, IL22, and IL17A), in these cells were decreased." (PMID 39327633, 2024). "In one study on colorectal cancer, PTX3 emerged as a significant prognostic factor; in comparison, other markers, such as IL-6 and TNF-α, did not demonstrate the same prognostic utility." (PMID 39594709, 2024). "During colorectal cancer surgery, patients who received an allogenic red blood cell (RBC) transfusion had a significantly increased concentration of plasma TNF-α after surgery compared to those who did not." (PMID 36765695, 2023). "After 48 h of treatment with a cytokine mixture, TNF-, IL-1, and IL-6 relative mRNA increased in HT-29 and HCT-116 colorectal cancer cells, compared to the negative control." (PMID 36104433, 2022). "Elevated concentrations of IL-8, TNFα, IL-12 (a heterodimer consisting of IL-12p40 and IL-12p70), GMCSF, and IFNγ in blood have been reported in colorectal cancer patients in some but not all studies." (PMID 20924374, 2010). "However, filtrates, IPA extracts, and EA extracts of ADS024 and DSM7 did not affect proinflammatory cytokine secretion (TNFα, IL-1β, and MIP-1α) in toxin-treated human colonic explants from colorectal cancer patients." (PMID 36704560, 2022). "However, TNF-α was increased in colorectal cancer cachexia patient, indicating that TNF-α might play a role in the development of cancer cachexia in colorectal cancer cachexia but not in gastric cancer cachexia." (PMID 31788012, 2019).
ankylosing spondylitis (511 papers, 2005 to 2026). An autoimmune chronic inflammatory disorder characterized by inflammation in the vertebral joints of the spine and sacroiliac joints. "Background/Objectives: Tumor necrosis factor (TNF) inhibitors are widely used in ankylosing spondylitis (AS), but data on cancer risk in this young population remain limited." (PMID 41302997, 2025). "Significant relationships between the IL5 rs2069812 and IL9 rs2069885 polymorphisms and response to anti-TNF treatment, expressed by the Bath Ankylosing Spondylitis Disease Activity Index (BASDAI) were observed." (PMID 36361964, 2022). "A long-term observational study using MRI and conventional radiography Which spinal lesions are associated with new bone formation in patients with ankylosing spondylitis treated with anti-TNF agents?" (PMID 34264363, 2022). "Anti-tumor necrosis factor agents are widely used in treating ankylosing spondylitis, but they increase the risk of infection by suppressing the immune response." (PMID 37274971, 2022). "This study is aimed at investigating IL-17A, IL-17F, IL-17RA, and IL-17RC polymorphisms as potential biomarkers of disease susceptibility, clinical parameters, and anti-TNF treatment outcome in a cohort of Polish ankylosing spondylitis patients." (PMID 34744511, 2021). "In both RA and Ankylosing spondylitis (AS), the efficiency of anti-TNF agents on bone loss has also been confirmed through BMD measurements using DXA." (PMID 34010320, 2021). "Most reports concern FMF associated ankylosing spondylitis with a good response to IL-1 inhibitors even if older studies showed also efficacy with TNF blocking agents." (PMID 32670263, 2020). "It is known that TNF-α has been associated with Ankylosing Spondylitis (AS) whose the unique hallmark is pathologic new bone formation." (PMID 28575129, 2017). "Numerous studies have investigated the association between tumor necrosis factor-α (TNF-α) −857 C/T polymorphism and the risk of developing ankylosing spondylitis." (PMID 27917334, 2016). "In recent years, four meta-analyses evaluated the association between TNF-α gene polymorphism and risk of developing ankylosing spondylitis." (PMID 27917334, 2016). "Certain studies have suggested that the tumor necrosis factor-α (TNF-α) −857 C/T polymorphism is associated with risk of ankylosing spondylitis." (PMID 27917334, 2016). "The TNF cluster genes are implicated in the susceptibility to certain immunopathological diseases such as ankylosing spondylitis." (PMID 27917334, 2016). "Numerous studies examining the association between the TNF-α −857 C/T polymorphism and risk of ankylosing spondylitis have been published in China recently, but results remain controversial." (PMID 27917334, 2016). "Odds ratios (ORs) and 95% confidence intervals (CIs) were used to estimate the association between TNF-α −857 C/T polymorphism and ankylosing spondylitis susceptibility." (PMID 27917334, 2016). "Numerous studies have evaluated the association between TNF-α polymorphisms and susceptibility to ankylosing spondylitis." (PMID 27917334, 2016). "Only one meta-analysis investigated the association between the TNF-α gene −857 C/T polymorphism and risk of developing ankylosing spondylitis." (PMID 27917334, 2016). "This study aims to investigate the prevalence of short-term and long-term adverse events associated with tumor necrosis factor-α (TNF-α) blocker treatment in Chinese Han patients suffering from ankylosing spondylitis (AS)." (PMID 25764452, 2015). "What is more, observation from previous studies showed that tumor necrosis factor-alpha (TNF α) and IL-1 are implicated in ankylosing spondylitis." (PMID 25889422, 2015). "Moreover, both conditions share key aspects of immune regulation, notably elevated T-cell-mediated responses and inflammatory cytokines like TNFα, IL-6, and IL-1β, reflecting an increased cardiovascular disease risk in ankylosing spondylitis patients." (PMID 39131703, 2024).